GLB1 (galactosidase beta 1)
Diseases named in the same sentence as GLB1 in open-access papers (continued):
Sharing a sentence is not in itself a finding about the gene and the disease.
GM1 gangliosidosis (continued). "GM1 gangliosidosis is a progressive, recessive, autosomal, neurodegenerative, lysosomal storage disorder that affects the brain and multiple systemic organs due to an acid β-galactosidase deficiency encoded by the GLB1 gene." (PMID 35625088, 2022). "GM1 gangliosidosis is a progressive, recessive, autosomal, neurodegenerative, lysosomal storage disorder that affects the brain and multiple systemic organs due to an acid β-galactosidase (GLB1, EC 3.2.1.23) deficiency encoded by the GLB1 gene." (PMID 35625088, 2022). "The gene mutated in GM1-gangliosidosis is β-galactosidase (GLB1)." (PMID 35890374, 2022). "On the contrary, both Morquio B and GM1 gangliosidosis arise from mutations in the GLB1 gene." (PMID 33266180, 2020). "Hypomyelination was reported in several LSDs, including GM1 gangliosidosis with deficiency in acid β-galactosidase due to GLB1 mutations, and GM2 gangliosidosis with deficiency in β-hexosaminidase A (Tay-Sachs disease, HEXA mutations) or β-hexosaminidases A and B (Sandhoff disease, HEXB mutations)." (PMID 29451896, 2018). "The rarity of GM1 gangliosidosis and thus, heterozygous GLB1 mutation carriers, poses a critical challenge to researchers attempting to achieve this and may explain recent failures to find a GLB1-PD association in genetic case-control studies." (PMID 34149605, 2021). "Autosomal recessive mutations in the galactosidase β1 (GLB1) gene cause lysosomal β-gal deficiency, resulting in accumulation of galactose-containing substrates and onset of the progressive and fatal neurodegenerative lysosomal storage disease, GM1 gangliosidosis." (PMID 31481471, 2020). "This study underscores the potential of the Magellan platform in identifying STAR molecules and provides a strong foundation for further optimization and preclinical validation in GLB1-related disorders, particularly GM1 gangliosidosis." (PMID 42074270, 2026). "Although both GM1 gangliosidosis and MPS IVB disease arise from pathogenic variants in the GLB1 gene, distinct molecular characteristics and mutation biases typically underlie each condition." (PMID 41154677, 2025). "The present study investigates the phenotypic and morphological changes of retinal ganglion cells and retinal glial cells in a late-onset Glb1−/− mouse model during the course of GM1-gangliosidosis." (PMID 40804287, 2025). "The present study demonstrates that the Glb1−/− mouse strain used in this investigation is suitable for characterizing the pathologic changes within the retina in a model of the adult form of GM1-gangliosidosis." (PMID 40804287, 2025). "GM1 gangliosidosis (MIM: 230500, 230600, 230650) is a lysosomal disease caused by biallelic pathogenic variants in GLB1 which encodes β-galactosidase (EC 3.2.1.23)." (PMID 39897471, 2025). "This study identified a novel mutation of the GLB1 gene in a Chinese family with GM1 gangliosidosis and provided new insights into the molecular characteristics and genetic counseling of GM1 gangliosidosis." (PMID 39902059, 2025). "The brains of Glb1−/− and Glb1+/− mouse models of GM1 gangliosidosis have shown activated subsets of Mφs and microglial cells and the massive production of IL1β and TNFα." (PMID 37189685, 2023). "Mutations in the GLB1 gene that affect GM1-beta-galactosidase activity and stability cause lysosomal accumulation of GM1 and severe neurocognitive decline, termed GM1 gangliosidosis." (PMID 37972730, 2023). "The efficacy of analogs of this vector containing wild-type mouse or feline GLB1 genes was studied in mouse and cat models of GM1-gangliosidosis." (PMID 36835039, 2023). "Cerebral cortex neurons, astrocytes, and microglial cells of Glb1−/− and Glb1+/− mouse models of GM1 gangliosidosis have shown excess accumulation of GM1." (PMID 37189685, 2023). "GM1 gangliosidosis (GM1) is a heterogenous lysosomal storage disorder, due to mutations in the Galactosidase Beta 1 gene (GLB1), with an age of onset ranging from infantile period to adulthood." (PMID 36671323, 2023).
GM1 gangliosidosis (continued). "Therapies for MPS IVB are rarely reported, but GT, ERT and SRT have been explored to treat GM1-gangliosidosis, which can give some hints about atypical functions of GLB1." (PMID 35246201, 2022). "In an attempt to validate the efficacy of the IgG-GLB1 fusion protein, a subrogate fusion protein comprrising the mouse TfRMAb fused to the human GLB1 was produced and tested in a mouse model of GM1-gangliosidosis." (PMID 35890374, 2022). "In a more recent study, researchers used human iPSCs to create GLB1 knockout cerebral organoids that recapitulated GM1 gangliosidosis by exhibiting progressive accumulation of gangliosides at 10 and 20 weeks in culture." (PMID 36003149, 2022). "Lastly, in a phase 1/2 safety and efficacy clinical trial (NCT03952637), AAV9/GLB1 will be administered by intravenous infusion to subjects with type II GM1 gangliosidosis (ages 2–12 years) or patients aged 6 months to 1 year with a type I GM1 gangliosidosis." (PMID 34604300, 2021). "There are five mouse models of GM1-gangliosidosis reported in the literature generated using different targeting strategies of the Glb1 murine locus." (PMID 34539759, 2021). "Chronic GLB1 overexpression in all three GM1 gangliosidosis patient fibroblast lines also coincides with the appearance of smaller fragments on the β-gal Western blot, which were not characterized further." (PMID 31481471, 2020). "Chronic cellular uptake of purified recombinant human b-Gal (rhb-Gal) or chronic lentiviral-mediated GLB1 overexpression in GM1 gangliosidosis patient fibroblasts coincides with profound secondary NEU1 deficiency." (PMID 31481471, 2020). "After 28 days of chronic GLB1 overexpression in GM1 gangliosidosis patient cells, the levels of β-gal activity reach supraphysiological levels corresponding to 355% of β-gal activity detected in fibroblasts from a normal individual." (PMID 31481471, 2020). "We also employed a lentivirus-mediated, CMV promoter–driven gene therapy approach to overexpress GLB1 in GM1 gangliosidosis patient fibroblasts and further understand how retention of overexpressed β-gal in the ER impacts on cellular stress." (PMID 31481471, 2020). "In a previous study, GLB1 overexpression in feline GM1 gangliosidosis fibroblasts has been shown to result in β-gal mislocalization and retention in the ER." (PMID 31481471, 2020). "In GM1 gangliosidosis, deficient lysosomal β-GAL activity due to a mutation in the GLB1 gene causes accumulation of GM1 ganglioside." (PMID 32302553, 2020). "Evidence of eosinophilic granules in neurons of a feline model of GM1 gangliosidosis treated with AAV-mediated GLB1 gene therapy has also been reported." (PMID 31481471, 2020). "A lentivirus-mediated, CMV promoter–driven WT GLB1 gene therapy approach was used to chronically overexpress β-gal in GM1 gangliosidosis patient fibroblasts and compared with an intermittent ERT approach with a single 24-h exposure to rhβ-gal." (PMID 31481471, 2020). "The treatment of GM1-gangliosidosis and MPS IVB patient fibroblasts with 20 to 500 μM DLHex-DGJ showed a 1.3- to 12.5-fold increase in GLB1 activity depending on the mutation, reaching values between 0.4% and 57.2% of those from wild-type fibroblasts." (PMID 31905715, 2019). "The deficient activity of the lysosomal hydrolase β-galactosidase (β-gal), coded by GLB1, can result in two distinguishable clinical entities, GM1-gangliosidosis and Morquio B syndrome." (PMID 31771289, 2019). "Oral treatment of a p.R201C GM1 gangliosidosis mouse model led to a significant increase in GLB1 activity in heart, liver, kidney, and brain, and to the reduction of GM1 gangliosides and autophagy biomarker (p62 and LC3-II) levels in brain samples." (PMID 31905715, 2019). "NOEV has an IC50 of 0.2 μM against human GLB1 and increased the enzyme activity between 1.2- and 5.1-fold in mouse fibroblasts expressing GLB1 carrying GM1-gangliosidosis (p.R201C and p.R201H/p.R457Q) or MPS IVB (p.W273L/p.Y83H) mutations." (PMID 31905715, 2019).
GM1 gangliosidosis (continued). "Reduction of substrate levels can be detected when GM1-gangliosidosis fibroblast (GLB1−/−) are treated with a corrective recombinant protein." (PMID 26958633, 2016). "We obtained a genetic diagnosis in 4/9 (44 %) families within known HSP genes (DDHD2 and CYP2U1), as well as perixosomal biogenesis disorders (PEX16) and GM1 gangliosidosis (GLB1)." (PMID 27679996, 2016). "By developing and characterizing a Neu3- and Glb1-double knockout mouse model to deplete Neu3, they found a drastically earlier onset of disease in mice, which now resembles more the infantile form of GM1 gangliosidosis in humans." (PMID 37972730, 2023). "The increased expression of Grp78 in GM1 gangliosidosis patient fibroblasts in response to virus-mediated GLB1 overexpression also appears to be time-dependent, with increased Grp78 protein levels only becoming apparent 7 days following transduction with LV-CMV-GLB1." (PMID 31481471, 2020). "To confirm the results thus far, we took advantage of a GM1 gangliosidosis animal model, the BKO mouse, which carries the null mutation of the Glb1 gene encoding β-galactosidase and mimics the disease phenotype, including GM1 ganglioside accumulation in neural cells." (PMID 32302553, 2020). "Furthermore, the same type of MPS, as in the case of MPS III, can be conditioned by defects in different genes, and conversely, pathogenic variants in the same gene can be associated with distinct disorders, as exemplified by MPS IVB and GM1 gangliosidosis, both resulting from GLB1 defects." (PMID 41154677, 2025). "Ganglioside-monosialic acid (GM1) gangliosidosis (ICD-10: E75.1; OMIM: 230500, 230600, 230650) is a rare autosomal recessive hereditary disease, lysosomal storage disorder caused by mutations in the GLB1 gene that lead to the absence or insufficiency of β-galactosidase." (PMID 38404665, 2024). "Lack of GLB1 caused lysosomal storage disorder and led to G(M1) gangliosidosis." (PMID 35127693, 2021). "Of note, unlike with the ERT approach, chronic lentivirus-mediated GLB1 overexpression in the GM1 gangliosidosis patient fibroblasts caused accumulation of a prelysosomal pool of β-gal, resulting in activation of the unfolded protein response and endoplasmic reticulum stress." (PMID 31481471, 2020). "However, deficient GLB1 activity is also found in another lysosomal storage disease (GM1 gangliosidosis), which is not classified as a MPS and, therefore, an identification of GLB1 deficiency alone cannot discriminate between these two conditions." (PMID 32403245, 2020). "The identification of an isolated, elevation of KS, without elevation of CS, using sensitive and specific LC-MS/MS methods for analyzing GAGs, narrowed the diagnosis to a GLB1-related disorder (MPS IVB, MIM: 253010 or GM1 gangliosidosis)." (PMID 39897471, 2025). "Future dose-ranging and reaccumulation studies in the GLB1 KO mouse model will help to titrate the ICV-ERT dose and dosing frequency for rhβ-gal in clinical trials for GM1 gangliosidosis patients." (PMID 31481471, 2020). "Contrary to cats, dogs and early onset forms of human GM1-gangliosidosis, the current Glb1−/− mice did not reveal a decreased amount of myelin." (PMID 32252429, 2020). "Histologically, the liver, kidney and bone lesions were also absent in the current Glb1−/− mice, with this being similar to the adult form of human GM1-gangliosidosis." (PMID 32252429, 2020). "However, T cell infiltration and activation as well as microglia/macrophage activation were prolonged in Glb1-/- mice upon TMEV infection, which may suggest that GM1 gangliosidosis leads to a dysregulated immune response during infection." (PMID 40270964, 2025).
lysosomal storage disorder (32 papers, 2010 to 2026). "While its role in MAFLD is less well understood, GLB1 dysfunction has been linked to lysosomal storage disorders and impaired autophagy." (PMID 41007773, 2025). "Autosomal recessive mutations in the galactosidase beta 1 (GLB1) gene encoding the lysosomal hydrolase β-galactosidase (β-Gal) manifest in phenotypically distinct GLB1-related lysosomal storage disorders (LSD)." (PMID 38019733, 2023). "Morquio B disease (MBD) is an ultra-rare lysosomal storage disease, which represents the relatively mild form of GLB1-associated disorders." (PMID 35882863, 2022). "Morquio B disease (MBD, MIM: 253010) or Mucopolysaccharidosis IVB is a lysosomal storage disorder associated with pathogenic variants in the GLB1 gene (NM_000404.4)." (PMID 35882863, 2022). "GM1 gangliosidosis is a lysosomal storage disorder mainly caused by the systemic accumulation of GM1 ganglioside due to a deficiency of the beta galactosidase (GLB1) hydrolase." (PMID 31776384, 2019). "Therefore, GLB1 mutation analysis is necessary for infantile patients with lysosomal storage disease or neurological degeneration." (PMID 39902059, 2025). "A smaller subset of mutations predominantly near the 3′ end of GLB1 can result in another lysosomal storage disease, Morquio B disease (mucopolysaccharidosis type IVB), which is characterized by primary lysosomal accumulation of the glycosaminoglycan keratan sulfate." (PMID 34539759, 2021). "Therefore, GLB1 mutation analysis must be considered in the infants with lysosomal storage disease as well as in the patients with ataxia and any other childhood and juvenile neurodegenerative symptoms." (PMID 28716012, 2017). "Pathogenic variants in the GLB1 gene may lead to reduced activity of the lysosomal hydrolase, β‐galactosidase, and result in lysosomal storage disorders: GM1 gangliosidosis (OMIM #230500) and mucopolysaccharidosis type IVB, also known as Morquio B Disease (MBD, OMIM #253010)." (PMID 36341176, 2022). "Pseudodeficiency variants were also identified in other lysosomal storage disorders, such as p.R247W and p.R249W in the HEXA gene, p.A300T in the IDUA gene, p.R595W in the GLB1 gene, p.D152N in the GUSB gene, and p.D313Y in the GLA gene." (PMID 40449593, 2025). "Morquio B disease (MBD) is an autosomal recessive GLB1-gene-related lysosomal storage disease, presenting with a peculiar type of dysostosis multiplex which is also observed in GALNS-related Morquio A disease." (PMID 33266180, 2020). "More specifically, the lysosomal storage disorder Galactosialidosis (GS), caused by the loss of function of PPCA/CTSA, results in the secondary combined deficiency of GLB1 and NEU138." (PMID 31776384, 2019). "Mutations in the CTSA gene, that encodes the protective protein/cathepsin A or PPCA, lead to the secondary deficiency of β-galactosidase (GLB1) and neuraminidase 1 (NEU1), causing the lysosomal storage disorder galactosialidosis (GS)." (PMID 23915561, 2013). "Of note, some of the lysosomal enzymes with elevated levels in MUT brain (GRN, HEXA, and GLB1 – M36) are also implicated in lysosomal storage disorders, where they generally have decreased, rather than increased, function or expression." (PMID 33749590, 2021). "In fact, isolated cases with GP hypointensities consistent with iron excess are known in at least 17 distinct genes, including AP4M1 and AP4S1, which, like FUCA1, GLB1, and TPP1, are involved in lysosomal disorders." (PMID 36233161, 2022).
prostate carcinoma (9 papers, 2015 to 2024). A carcinoma that arises from epithelial cells of the prostate gland. "In prostate cancer patients, increased expression of β-galactosidase (GLB1) was associated with a reduced risk of recurrence." (PMID 27703211, 2016). "Additionally, increased GLB1 is a valuable marker in formalin-fixed paraffin-embedded tissues for the senescence-like phenotype and associates with improved prostate cancer outcomes." (PMID 27489354, 2016). "In LNCaP prostate cancer cells, expression of GLB1 is increased after androgen deprivation treatment, which is the standard treatment for prostate cancer." (PMID 35246201, 2022). "One such indicator, a lysosomal-beta-galactosidase (GLB1) that hydrolyzes beta-galactose from glycoconjugates and represents the origin of SA-ß-gal, was reported as a reliable senescence biomarker in prostate cancer." (PMID 32849491, 2020). "In this first assessment of senescence after ADT in prostate cancer, we find senescence to be induced preferentially in intermediate grade versus high grade cancer and that GLB1 accumulates over time consistent with a delayed entry of cells into senescence." (PMID 28234906, 2017). "Lysosomal β-galactosidase (GLB1) hydrolyzed β-galactosidase from a sugar conjugate, representing the origin of the aging-associated β-galactosidase SA-SS-GAL, was reported to be a reliable biomarker of aging in prostate cancer." (PMID 36568076, 2022). "Studies suggest the involvement of GLB1 in prostate cancer, glioma, and other malignancies." (PMID 36313783, 2022). "Using a new GLB1 antibody, senescence biology was investigated in prostate cancer (PCa) tissues." (PMID 25876105, 2015). "However, increased GLB1 levels lead to increased survival without prostate-specific antigen (PSA) in prostate cancer, which is contradictory with our outcomes, as well as the specific roles of GLB1 in glioma need to be further explored." (PMID 39707577, 2024).
Morquio syndrome (7 papers, 2012 to 2025). "Mutations in the GALNS or GLB1 genes must be identified to differentiate between type A and type B Morquio syndrome." (PMID 41141144, 2025). "Mucopolysaccharidosis IV (MPS IV, Morquio syndrome) is another autosomal recessive MPS subtype, associated with pathogenic variants in GALNS and GLB1." (PMID 39940729, 2025). "There are two types of Morquio syndrome: type A, due to deficiency of N-acetyl-galactosamine-6-sulfatase (GALNS), and type B, due to deficiency of beta-galactosidase (GLB1)." (PMID 41141144, 2025). "Morquio B disease (MBD) is a distinct GLB1‐related dysostosis multiplex presenting a mild phenocopy of GALNS‐related Morquio A disease." (PMID 34258138, 2021). "Currently, two genetic conditions are known to cause Morquio‐like dysostosis multiplex: GALNS‐related Morquio A disease (OMIM 25300) and GLB1‐related MBD." (PMID 34258138, 2021). "Currently two genetic conditions are known to cause Morquio syndrome: GALNS‐related Morquio‐A disease (OMIM 25300) and GLB1‐related Morquio‐B disease (MBD)." (PMID 32071837, 2020). "The Morquio syndrome (MPS IV) can be caused by a mutation either in the N-acetylgalactosamine-6-sulfatase (GALNS) gene (MPS type IVA), or in the gene for galactosidase beta 1 (GLB1; MPS type IVB)." (PMID 37441579, 2023).
mucopolysaccharidosis type IVB (6 papers, 2011 to 2023). "The GLB1 mutations underlying Morquio B syndrome affect the catabolism of KS but have little effect on GM1 gangliosides." (PMID 30442161, 2018). "Mutations in the GLB1 gene are responsible for two allelic disorders: the neurodegenerative GM1 gangliosidosis (non-MPS) disorder (MIM 230500) and the rare MPS IVB (Morquio B) syndrome (MIM 253010)." (PMID 30442161, 2018).
gangliosidosis (5 papers, 2020 to 2026). A group of autosomal recessive lysosomal storage disorders marked by the accumulation of gangliosides. "GM1-Gangliosidosis (OMIM #230500) is caused by a mutation in the GLB1 gene, resulting in a deficiency of the lysosomal enzyme β-Galactosidase and the subsequent accumulation of GM1-Gangliosidosis." (PMID 38617391, 2024). "Type 1 GM1-Gangliosidosis (OMIM #230500) is caused by mutations in GLB1 (beta-galactosidase-1) leading to the accumulation of GM1 gangliosides and presenting with prompt psychomotor dysfunction and general CNS degeneration within the first 6 months of life." (PMID 32351971, 2020).
glioma (4 papers, 2022 to 2025). A benign or malignant brain and spinal cord tumor that arises from glial cells (astrocytes, oligodendrocytes, ependymal cells). "Inspired by this, a glucose metabolism‐related gene (GMG)‐based model, including LDHA, GUSB, GLB1, GALM, and FBP1, was proposed based on protein‒protein interaction analysis to predict the prognosis of patients with glioma." (PMID 39830021, 2025).